YTHDF1 (YTH N6-methyladenosine RNA binding protein F1)
Diseases named in the same sentence as YTHDF1 in open-access papers (continued):
Sharing a sentence is not in itself a finding about the gene and the disease.
Obesity (11 papers, 2021 to 2025). Accumulation of substantial excess body fat. "The dysregulation of RBPs, including HuR, PTB, and YTHDF1, is linked to metabolic diseases such as obesity, diabetes, and non-alcoholic fatty liver disease." (PMID 40732992, 2025). "Adipocyte-specific Ythdf1 deficiency exacerbates obesity-induced metabolic defects and inhibits beiging of inguinal white adipose tissue (iWAT) in male mice." (PMID 36914671, 2023). "Here, we show that YTHDF1 may be an potential therapeutic target for the management of obesity-associated diseases." (PMID 36914671, 2023). "Thus, YTHDF1 may have applications in therapeutic strategies for the management of obesity-associated metabolic diseases." (PMID 36914671, 2023). "“Writers” like METTL3 and METTL14 add m6A marks, “erasers” such as fat mass and obesity-associated protein (FTO), ALKBH5 remove them, and “readers” including YTHDF1, YTHDC1 recognize the marks, mediating functional outcomes." (PMID 40442779, 2025). "The m6A RNA modification was detected to be a key regulator of obesity, with YTHDF1 acting as a white adipose tissue metabolism regulator." (PMID 39057082, 2024). "Deletion of Ythdf1 exacerbated obesity, reduced rectal temperature, and downregulated the thermogenic genes." (PMID 36914671, 2023). "By contrast, male mice with WAT-specific YTHDF1 overexpression are resistant to obesity and shows promotion of beiging." (PMID 36914671, 2023). "Mice with Ythdf1 overexpression in iWAT showed significant alleviation of obesity-related symptoms, including glucose intolerance, insulin resistance, and TG synthesis." (PMID 36914671, 2023). "Collectively, these results demonstrated that WAT-specific YTHDF1 overexpression protected against HFD-induced obesity and metabolic disorders." (PMID 36914671, 2023). "Collectively, our data demonstrated that adipocyte-specific knockout of Ythdf1 aggravated the detrimental effects of obesity." (PMID 36914671, 2023). "Our results highlighted an important role of YTHDF1 in preventing obesity and provided potential targets for the treatment of obesity-associated metabolic diseases." (PMID 36914671, 2023). "By contrast, WAT-specific YTHDF1 overexpression tempered obesity-related symptoms." (PMID 36914671, 2023). "As expected, YTHDF1 expression alleviated HFD-induced obesity." (PMID 36914671, 2023). "In PBMCs, the eraser ALKBH5 and the readers YTHDF1 and YTHDF3 associate with obesity." (PMID 34950106, 2021). "Furthermore, in human cohorts, the study found that the writers WTAP and VIRMA, the eraser ALKBH5, and reader proteins such as YTHDF1, YTHDF2, and YTHDC1 are associated with obesity by comparing gene expression of m6A regulators in adipose tissue between individuals with obesity and lean controls." (PMID 40428320, 2025). "Together, these findings demonstrated that YTHDF1 played important roles in promoting beiging and antagonizing HFD-induced obesity." (PMID 36914671, 2023). "Taken together, we demonstrated that LEO improves oxidative stress and vascular remodeling induced by obesity and targets YTHDF1, raising the possibility of LEO treating other obesity-related metabolic syndromes." (PMID 35883829, 2022). "We hypothesized that WAT-specific YTHDF1 overexpression may promote the beiging process and ameliorate HFD-induced obesity." (PMID 36914671, 2023). "The negative correlation of YTHDF1 expression in WAT with obesity implies a role of this protein in adipose tissue metabolism." (PMID 36914671, 2023). "We demonstrated that YTHDF1 promotes mRNA translation to induce WAT beiging and alleviate obesity." (PMID 36914671, 2023). "Here the authors report that the m6 A RNA modification reader YTHDF1 promotes WAT thermogenesis in a study with male mice, and may be a potential target for the treatment of obesity." (PMID 36914671, 2023).
Obesity (continued). "Mechanistically, m6A-dependent TNF receptor-associated factor 4 (TRAF4) expression upregulation by AlkB homolog 5 (ALKHB5) and YTH-domain family 1 (YTHDF1), which thus promoted PPAR-γ degradation by the ubiquitin-proteasome system, contributed to CUR-induced obesity prevention." (PMID 36233207, 2022). "Importantly, the published sequencing data revealed decreased YTHDF1 mRNA expression in WAT of individuals with obesity compared with that in nonobese individuals." (PMID 36914671, 2023).
pancreatic cancer (11 papers, 2020 to 2024). "Notably, YTHDF1 is associated with the immune microenvironment and prognosis of pancreatic cancer." (PMID 36999016, 2023). "For example, ZC3H13 mediates m6A modification of CENPK mRNA to increase translation of PHF10 in a YTHDF1-dependent manner, which in turn inhibits pancreatic cancer." (PMID 38351022, 2024). "A recent study found that a novel antineoplastic drug, Olean-28,13β-lactam (B28), inhibits glutamine metabolism by reducing the expression of YTHDF1, which induces pancreatic cancer cell death." (PMID 36999016, 2023). "ZC3H13 (11%), RBM15B (9%), YTHDF1 (8%), and YTHDC1 (6%) frequently occurred genetic mutations in pancreatic cancer." (PMID 34603372, 2021). "YTHDF1 has been shown to be involved in the regulation of colorectal and pancreatic cancer." (PMID 34187307, 2021). "Given the significantly lower expression of YTHDF1 in the stromal cells and positive correlation with OS of patients with PDAC observed in this study, it will be interesting to determine whether stromal YTHDF1 also exerts an iron-metabolism dependent protective role in pancreatic cancer." (PMID 34733841, 2021). "This study found the significantly upregulated METTL3 in pancreatic cancer, and METTL3 direct target DDX23 mRNA and promotes its translation in a YTHDF1-dependent pathway." (PMID 36977668, 2023). "Furthermore, pancreatic cancer patients with lower METTL3, METTL14, RBMX, FTO, ALKBH5, YTHDF1, and YTHDC1 mRNA expression levels or higher VIRMA, HNRNPA2B1, EIF3A, IGF2BP1, IGF2BP2, and IGF2BP3 mRNA expression levels had significantly poorer OS (P < 0.05)." (PMID 34330301, 2021).
ocular melanoma (9 papers, 2019 to 2025). A melanoma that arises from the structures of the eye or ocular adnexa. "For instance, m6A methylation on histidine triad nucleotide-binding protein 2 (HINT2), a tumor suppressor, is recognized by YTHDF1 that promotes its translation and significantly inhibits the progression of ocular melanoma cells in ocular melanoma." (PMID 39087001, 2024). "YTHDF1 suppresses ocular melanoma through modulation of mRNA translation of histidine triad nucleotide-binding protein 2, a tumor suppressor in ocular melanoma." (PMID 32513173, 2020). "The ‘readers’, such as YTHDF1, could inhibit ocular melanoma by mediating m6A modification of HINT2 mRNA." (PMID 34446007, 2021). "m6A modification was decreased in ocular melanoma due to METTL3 downregulation and ALKBH5 upregulation, which promoted YTHDF1-mediated translation of histidine triad nucleotide-binding protein 2 (HINT-2), a tumor suppressor of ocular melanoma." (PMID 35164788, 2022). "Mechanistically, YTHDF1 promoted the translation of methylated HINT2 mRNA, a tumor suppressor in ocular melanoma." (PMID 31722709, 2019). "Mechanistically, m6A methylation recognized by YTH N6-methyladenosine RNA binding protein 1 (YTHDF1) promotes translation of histidine triad nucleotide-binding protein 2 (HINT2), a tumor suppressor in ocular melanoma." (PMID 31722709, 2019). "Mechanistically, YTHDF1 promotes the translation of methylated mRNA of HINT2, a tumor suppressor in ocular melanoma." (PMID 31722709, 2019). "Moreover, YTHDF1 has been shown to augment the translation of methylated HINT2 mRNA, thereby suppressing the malignant progression of ocular melanoma." (PMID 40251202, 2025). "In addition to YTHDF1 and METTL3, which affect ocular melanoma by influencing their downstream target genes, FTO has also been found to play a key role in ocular melanoma." (PMID 41315216, 2025). "With the help of YTHDF1, the translation of methylated HINT2 mRNA, a tumour suppressor of ocular melanoma, was significantly accelerated, meaning m6A modification obviously inhibits the progression of ocular melanoma." (PMID 32303268, 2020).
pulmonary hypertension (9 papers, 2021 to 2025). Increased pressure within the pulmonary circulation due to lung or heart disorder. "In the vascular remodeling of pulmonary hypertension, YTHDF1 promoted pulmonary hypertension by enhancing melanoma-associated antigen D1 expression." (PMID 37210465, 2023). "In addition, YTHDF1 promotes pulmonary hypertension by modulating the phenotype of pulmonary artery smooth muscle cells." (PMID 39936952, 2025). "Notably, YTHDF1 knockdown attenuated ameliorated pulmonary artery smooth muscle cell proliferation, phenotypic switching, and the development of pulmonary hypertension by enhancing MAGED1 translation both in vivo and in vitro." (PMID 38509077, 2024). "YTHDF1 was reported to regulate pulmonary hypertension through the control of MAGED1." (PMID 36911406, 2023). "It has been shown that YTHDF1 was up-regulated in human and rodent pulmonary hypertension samples, knockdown of YTHDF1 ameliorated PASMC proliferation, phenotypic switching, and pulmonary hypertension development via promoting the translation of MAGED1 both in vivo and in vitro." (PMID 36650570, 2023). "In a rat model of hypoxia-inducted pulmonary arterial hypertension and in hypoxia-induced or PDGF-BB-induced PASMCs, both METTL3 and YTHDF1 are upregulated." (PMID 39155349, 2024).
esophageal squamous cell carcinoma (8 papers, 2020 to 2025). Esophageal squamous cell carcinoma (ESCC) is a type of esophageal carcinoma (EC) that can affect any part of the esophagus, but is usually located in the upper or middle third. "In esophageal squamous cell carcinoma, YTHDF1 is involved in m6A-dependent regulation, and c-MYC is a key downstream effector in the oncogenic pathway mediated by METTL3/YTHDF-coupled epitranscriptomal regulation." (PMID 41167308, 2025). "In detail, YTHDF1-regulated LncRNA HCP5 has been evidenced to involve in progression of esophageal squamous cell carcinoma." (PMID 37365581, 2023). "In esophageal squamous cell carcinoma, ERBB2 was identified as the target of FTO using m6A-seq and RNA-seq assays, and YTHDF1 then binds and stabilizes ERBB2 mRNA." (PMID 36360294, 2022). "METTL3, WTAP, IGF2BP3, YTHDF1, HNRNPA2B1 and HNRNPC were markedly increased in esophageal squamous cell carcinoma (ESCC) and positively related to the expression of PD-1, whose copy number dynamically affects the enrichment of tumor-infiltrating immune cells." (PMID 36225914, 2022). "YTHDF1 restrains esophageal squamous cell carcinoma (ESCC) by interacting with long intergenic non-protein coding RNA 278 (LINC00278), but ALKBH5 harbors an opposite function." (PMID 32767982, 2020).
head and neck squamous cell carcinoma (8 papers, 2020 to 2025). A squamous cell carcinoma that arises from any of the following anatomic sites: lip and oral cavity, nasal cavity, paranasal sinuses, pharynx, larynx, and salivary glands. "In head and neck squamous cell carcinoma, YTHDF1 regulates iron metabolism by methylating TFRC (m6A methylation)." (PMID 37088822, 2023). "Furthermore, there is an intense connection between the expression of YTHDF1 and the malignant characteristics of head and neck squamous cell carcinoma (HNSCC) tumors." (PMID 39821576, 2025). "It has been shown that in head and neck squamous cell carcinomas (HNSCCs), the YTH structural domain of the m6A reader YTHDF1 interacts with the 3′UTR and 5′UTR of TFRC mRNA." (PMID 38550378, 2024).
Merkel cell carcinoma (8 papers, 2020 to 2023). "Merkel Cell Carcinoma normally outburst by the Merkel cell polyomavirus (MCPyV) and YTHDF1 has high copy gains and was highly expressed in Merkel cell carcinoma, which played an oncogenic role by promoting the translation initiation factor eIF3." (PMID 36707507, 2023). "We identified YTHDF1, a protein that is a reader of N6-methyladenosine (m6A) RNA modifications, to have high copy gains and to be highly expressed in Merkel cell carcinoma." (PMID 31947544, 2020). "This study is the first step in elucidating the role of YTHDF1 m6A reader and introducing a novel mechanism of tumorigenesis in Merkel cell carcinoma through the activation of cap-dependent translation." (PMID 31947544, 2020). "High levels of YTHDF1 could predict the poor prognosis of patients with Merkel cell carcinoma (MCC)." (PMID 36835633, 2023). "YTHDF1 has high copy gains and overexpression in Merkel cell carcinoma, YTHDF1 amplification was positively regulate the expression of MCPyV, and knockdown of YTHDF1 significantly inhibited the Merkel cell proliferation via down-regulate the translation initiation factor eIF3." (PMID 36650570, 2023). "Overall, our study could establish a novel tumorigenic mechanism in fatal skin cancer, Merkel cell carcinoma, that happens due to the upregulation YTHDF1 m6A reader, and by activation of translational initiation factors eIF3A and 3B." (PMID 31947544, 2020). "This study underscores the role of a m6A reader, YTHDF1 in Merkel cell carcinoma." (PMID 31947544, 2020). "Interestingly, knockdown of YTHDF1 in Merkel cell carcinoma (MCC) cell lines negatively affected the translation initiation factor eIF3 and reduced proliferation and clonogenic capacity in vitro." (PMID 31947544, 2020). "Since m6A modification has been reported for several viruses similar to MCPyV and because YTHDF1 is a well-characterized reader of m6A in humans, we set out to investigate the presence of m6A RNA modification in mRNA derived from the integrated sequence of MCPyV in Merkel cell carcinoma." (PMID 31947544, 2020). "In this study, we demonstrate upregulation of YTHDF1 (m6A reader) by a gene copy gain mechanism, and the presence of m6A in multiple sites of MCPyV sequence in Merkel cell carcinoma that has not been reported so far." (PMID 31947544, 2020).
acute myeloid leukemia (7 papers, 2021 to 2024). Acute myeloid leukemia (AML) is a group of neoplasms arising from precursor cells committed to the myeloid cell-line differentiation. "The mutations of m6A regulatory genes, METTL3, METTL14, YTHDF1, YTHDF2, FTO, and ALKBH5, have been identified in acute lymphoblastic leukemia, multiple myeloma, and acute myeloid leukemia (AML)." (PMID 33898522, 2021). "Furthermore, the results showed that YTHDF1 mRNA expression was significantly high among most cancer types except LAML (acute myeloid leukemia), which was consistent with the Oncomine database results." (PMID 34026603, 2021). "In acute myeloid leukemia (AML), Tegaserod can inhibit the translation of cyclin E2 regulated by YTHDF1, thereby affecting the proliferation and survival abilities of AML cells." (PMID 38790013, 2024).
colon adenocarcinoma (7 papers, 2021 to 2023). "To comprehensively understand the role of ALKBH5 and YTHDF1 in tumor immunity, we analyzed the transcriptome profiling data of colon adenocarcinoma from The Cancer Genome Atlas (TCGA) and Gene Expression Omnibus (GEO)." (PMID 34079761, 2021). "This study aimed to determine the relationship between ALKBH5/YTHDF1 and immunological characteristics of colon adenocarcinoma (COAD)." (PMID 34079761, 2021). "ALKBH5 and YTHDF1 may remarkably influence the immune contexture of colon adenocarcinoma." (PMID 34079761, 2021).
hepatoblastoma (7 papers, 2020 to 2024). Hepatoblastoma (HB) is a malignant hepatic tumor and is the most common pediatric liver cancer. "The YTHDF1 rs6090311 G allele protects carriers from developing hepatoblastoma risk, and eQTL analysis elucidated the correlation between the YTHDF1 rs6090311 polymorphism and downregulated expression of its surrounding genes." (PMID 37850543, 2024). "YTHDF1 gene rs6090311 was associated with decreased hepatoblastoma risk, whereas rs7766006 in the WTAP gene was associated with an increased risk of hepatoblastoma." (PMID 35986847, 2022). "In our recent study, we evaluated the association between two SNPs (rs6011668 C>T and rs6090311 A>G) in the YTHDF1 gene and hepatoblastoma susceptibility." (PMID 33758623, 2021). "We also investigated the role of YTHDF1 gene SNPs on the risk of hepatoblastoma using 313 hepatoblastoma cases and 1446 controls from China." (PMID 34151473, 2021). "Overall, we identified that the YTHDF1 gene rs6090311 A>G polymorphism was associated with a decreased hepatoblastoma risk." (PMID 32742460, 2020). "With this in mind, we performed a relatively large case-control study to identify more hepatoblastoma susceptibility genetic variants in the YTHDF1 gene." (PMID 32742460, 2020). "In conclusion, our results indicate that the rs6090311 A>G in the YTHDF1 gene is related to decreased hepatoblastoma risk." (PMID 32742460, 2020). "In all, we present the first epidemiology evidence supporting the involvement of YTHDF1 gene polymorphisms in hepatoblastoma risk." (PMID 32742460, 2020). "We further attempted to interpret the possible mechanism of YTHDF1 gene rs6090311 A>G-mediated hepatoblastoma risk." (PMID 32742460, 2020). "In addition, an assessment of single nucleotide polymorphisms (SNPs) in the YTHDF1 gene in 313 cases of hepatoblastoma showed that rs6090311 A>G was correlated with a reduced risk of hepatoblastoma." (PMID 36999016, 2023). "In this study, we aimed to investigate whether single nucleotide polymorphisms (SNPs) in the YTHDF1 gene could predispose to hepatoblastoma." (PMID 32742460, 2020). "We used TaqMan assay to genotype two YTHDF1 SNPs (rs6011668 C>T and rs6090311 A>G) in a Chinese population composed of 313 subjects with hepatoblastoma and 1446 controls from seven hospitals." (PMID 32742460, 2020). "In the current study, we assayed the genotype frequencies of two YTHDF1 SNPs in a representative set of 313 hepatoblastoma cases and 1446 controls." (PMID 32742460, 2020). "Our group has previously reported that many genetic variants of genes encoding RNA m6A and m7G methyltransferase, demethylase, and m6A-reading proteins confer hepatoblastoma susceptibility, including METTL3, METTL4, AlkB homolog 5 (ALKBH5), FTO, YTHDC1, YTHDF1, WTAP, WDR4, and METTL1." (PMID 37531210, 2023). "Further studies are therefore warranted to delineate genetic contributions of YTHDF1 to hepatoblastoma susceptibility in populations of non-Chinese ancestries." (PMID 32742460, 2020).
liver fibrosis (7 papers, 2021 to 2026). "Conversely, O‐GlcNAcylation of ECM‐associated YTHDF1 boosts its phase separation; YTHDF1 condensates stabilize collagen I‐encoding mRNAs to promote ECM deposition, and its dysregulation links to hepatic fibrosis." (PMID 41573248, 2026). "For example, YTHDF1 activates autophagy by stabilizing BECN1, leading to hepatic stellate cell ferroptosis and ameliorating liver fibrosis in murine models." (PMID 39897540, 2025). "In liver fibrosis, ALKBH5 inhibits the mitochondrial fission, proliferation and migration of hematopoietic stem cells in a YTH domain family protein 1 (YTHDF1)‐dependent manner by reducing the m6A modification of Drp1, which provides a valuable strategy for liver fibrosis diagnosis and therapy." (PMID 37537731, 2023). "In the liver fibrosis mice, the m6A methylation abundance was significantly decreased as well as the expressions of WTAP, ALKBH5 and YTHDF1, and the decreased expression of WTAP has been shown to induce the development of liver fibrosis and promote hepatic stellate cell (HSC) activation." (PMID 37227534, 2023).